REN (renin)
Diseases named in the same sentence as REN in open-access papers (continued):
Sharing a sentence is not in itself a finding about the gene and the disease.
COVID-19 (continued). "Furthermore, it is essential to note that future studies are needed to determine whether modulation of ACE2-SARS-CoV-2 interaction or the renin-angiotensin system could mitigate ASCVD following COVID-19." (PMID 39113913, 2024). "The proposed mechanisms by which vitamin D may influence COVID-19 outcomes include the suppression of the renin-angiotensin system, reduction of pro-inflammatory cytokine production, and mitigation of the cytokine storm-a hyperinflammatory state contributing to severe disease manifestations." (PMID 39564063, 2024). "In the case of COVID-19, a possible explanation for the correlation between electrolyte imbalance and mental fatigue in females could be represented by the different sex-dependent expressions of the brain renin–angiotensin system (RAS)." (PMID 37297898, 2023). "It was hypothesized that the renin–angiotensin–aldosterone system (RAAS) has an essential role in SARS-CoV-2 infection, and its genes polymorphisms may have a role in elucidating the multi-organ and multi-system affection of COVID-19." (PMID 36673116, 2023). "Moreover, COVID-19 mediated angiotensin II accumulation may promote renin–angiotensin–aldosterone (RAAS) activation, leading to inflammation, fibrosis and vasoconstriction." (PMID 35669127, 2022). "The pathophysiology of COVID-19-associated AKI could be attributed to unspecific mechanisms, as well as COVID-19-specific mechanisms such as direct cellular injury, an imbalanced renin-angiotensin-aldosterone system, pro-inflammatory cytokines elicited by the viral infection and thrombotic events." (PMID 36358895, 2022). "Studies reporting increased ACE2 expression with angiotensin (Ang)-converting enzyme-1 (ACE-1) inhibitors (ACEIs) and Ang type 1 receptor (AT1R) antagonists (ARBs) suggested that renin-angiotensin system (RAS) blockers could worsen the prognosis of COVID-19 patients." (PMID 35563515, 2022). "However, even given that COVID-19 pathophysiology may be driven by an imbalance in the renin-angiotensin system (RAS), we were still far from understanding the complexity of the mechanisms which are controlled by ACE2 in different cell types." (PMID 36519165, 2022). "In addition, the current data show that IMQ treatment could produce the altered metabolism (i.e., sphingolipid signaling pathway, coronavirus disease—COVID-19, steroid degradation, and renin secretion) induced by skin microbiota." (PMID 34050205, 2021). "Studies examining the association between renin–angiotensin system inhibitor use and COVID-19 susceptibility have since been published that report no COVID-19 risk or a lower risk associated with use of angiotensin-converting enzyme inhibitors (ACEIs) and angiotensin receptor blockers (ARBs)." (PMID 33342753, 2021). "Finally, disruption of the renin-angiotensin system (RAS) may also play a role in COVID-19-mediated ICH; down-regulation of endothelial ACE2 receptors can cause dys-autoregulation of cerebral blood flow." (PMID 33547527, 2021). "The exact role renin-angiotensin-aldosterone system agents have on both infection rates and mortality remains controversial, and the consequences of their subsequent discontinuation in the hospital setting in COVID-19 remain unclear." (PMID 33370368, 2020). "In addition, COVID-19 promotes an imbalanced activation of the renin–angiotensin–aldosterone system (RAAS), which induces the downregulation of the membrane-bound ACE2 receptor that promotes the accumulation of angiotensin II by lowering its degradation into angiotensin 1–7." (PMID 33334023, 2020). "In the context of the ongoing SARS-CoV-2 pandemic and considering the involvement of humoral disbalance in the pathogenesis of ARDS, targeting the renin–angiotensin system and reducing the pathogen’s cell entry could be a promising therapeutic strategy in the struggle against COVID-19." (PMID 33126657, 2020).
COVID-19 (continued). "The emergence of SARS-CoV-2 and the subsequent COVID-19 pandemic have spurred extensive research into the relationship between the renin-angiotensin system (RAS) and COVID-19." (PMID 40754875, 2025). "Earlier studies have described the aldosterone/renin ratio in COVID-19 patients, but our study was the first to describe the AA2R in patients with COVID-19." (PMID 39821855, 2025). "The impact of COVID-19 on AAA is multifaceted, precipitating disruptions in the immune system, the renin-angiotensin-aldosterone system (RAAS), and thrombotic equilibrium." (PMID 39742024, 2024). "As a key enzyme of the renin-angiotensin system (RAS), angiotensin-converting enzyme 2 (ACE2) is a validated receptor for SARS-CoV-2, linking RAS to COVID-19." (PMID 39318909, 2024). "The pathophysiology of COVID-19 AKI involves very robust local and systemic inflammatory and immune responses leading to endothelial injury and activation of coagulation and the renin–angiotensin system evidenced by a rise in inflammatory markers." (PMID 37624325, 2023). "ACE belongs to the renin–angiotensin–aldosterone system (RAAS), which has a significant role in COVID-19; this enzymatic chain not only controls the pulmonary system, but also regulates the renal and circulatory systems." (PMID 36673116, 2023). "In particular, animal studies have shown that renin–angiotensin–aldosterone system (RAAS) inhibitors increase the expression of ACE2 receptors, which constitute one of the initial steps in COVID-19 viral entry into cells." (PMID 36732874, 2023). "In patients with COVID-19, SARS-CoV-2 enters the cells using angiotensin-converting enzyme 2 (ACE2) as a receptor, which is one of the main effectors of the brain renin–angiotensin system (RAS)." (PMID 37297898, 2023). "The renin-angiotensin system, and specifically, ACE2 receptor, the receptor for COVID-19, is increased in bronchial biopsy specimens of patients with chronic systemic HTN." (PMID 36996126, 2023). "In COVID-19, the main target of SARS-CoV-2 is ACE2 receptor, a critical enzyme of the renin–angiotensin–aldosterone system (RAAS), which promotes oxidative stress via stimulating NADPH Oxidase, an action principally mediated by Ang II." (PMID 37222866, 2023). "Thus, ACE2 plays an important role in inflammation, and its down-regulation may aggravate COVID-19 via the renin-angiotensin system, including by promoting pathological changes in lung injury and involving inflammatory responses in conjunction with the release of cytokines, especially IL-6." (PMID 35053224, 2022). "Vitamin D can also protect against COVID-19 by modulating innate and adaptive immunity, increasing ACE2 expression, and inhibiting the renin–angiotensin–aldosterone system." (PMID 36142634, 2022). "One study put forward a hypothesis on the role of renin–angiotensin system (RAS) pathway genes including ACE2 (rs2285666, rs1978124, rs714205) in COVID-19 prognosis, suggesting that inherited genetic predispositions could forecast the degree of severity of COVID-19." (PMID 36015068, 2022). "Molecular docking studies are of great importance to discover potential drugs against COVID-19, which involves the cardiovascular system as infection is initiated by the entry of the S-protein via ACE2, a peptide of the renin-angiotensin system (RAS)." (PMID 35632769, 2022). "The angiotensin converting enzyme 2 (ACE2) plays an important regulatory role in the renin-angiotensin-system (RAS) and has been shown to be protective against comorbidities known to worsen COVID-19 outcomes." (PMID 35284910, 2022). "A major role of the tissue renin-angiotensin system (RAS) in the pathophysiology and severity of COVID-19 has been suggested." (PMID 35203711, 2022). "A considerable number of studies have suggested the major role of the tissue renin-angiotensin system (RAS) in the pathophysiology and severity of COVID-19." (PMID 35203711, 2022).
COVID-19 (continued). "In addition, the adverse outcomes of COVID-19 may be circumvented by vitamin D by modulating the activity of the renin-angiotensin system (RAS) and the expression of the angiotensin-2 converting enzyme (ACE2), which reduces pulmonary permeability in the ARDS experimental model." (PMID 36295519, 2022). "Herein, we discuss different therapeutic mechanisms of hAECs such as immunomodulation, renin–angiotensin–aldosterone system (RAAS) regulation, alveolar fluid clearance, coagulopathy elimination, and regenerative capacity in COVID-19." (PMID 35337387, 2022). "Mechanisms contributing to cardiovascular sequelae in post-acute COVID-19 seem to be downregulation of ACE2 and renin-angiotensin-aldosterone system (RAAS), cytokine storm-related deterioration of myocardial integrity, pericarditis, and arrhythmias." (PMID 35721785, 2022). "Renin–angiotensin system (RAS) signaling, specifically angiotensin-converting enzyme 2 (ACE2), was identified in the pathogenesis of COVID-19." (PMID 34554559, 2021). "Increased levels of gonadotropin and androgen, dysregulated renin-angiotensin-aldosterone system (RAAS), hyper-coagulation and chronic inflammation are common conditions observed among OC and severe cases of COVID-19." (PMID 33632295, 2021). "It has also been proposed that cardiovascular medication, in particular, inhibitors of the Renin-Angiotensin-Aldosterone system (RAASi) elevate serum ACE2 activity, potentially contributes to the mortality of COVID-19." (PMID 33469835, 2021). "Our identified ACE and REN inhibitor captopril and AGTR1 targeting losartan are potential anti-COVID-19 drugs." (PMID 34067609, 2021). "Given that the renin–angiotensin system and ACE2 expression can be overactivated by hyperglycemia, poor glucose control in COVID-19 patients is likely to facilitate virus entry and infection." (PMID 33480978, 2021). "A recent study reported the super activation of RAS in patients with COVID-19 and AKI; the levels of renin and aldosterone were increased and correlated with reduced sodium excretion." (PMID 34497535, 2021). "Keywords used for the search were COVID-19, SARS-CoV-2, Coronavirus diseases 2019, Angiotensin-converting enzyme inhibitors (ACEI), Angiotensin 11 receptor blockers (ARB) and Renin-Angiotensin-Aldosterone System (RAAS)." (PMID 33778087, 2021). "RAGE is essential to the deleterious effects of the renin–angiotensin system (RAS), which participates in infection and multiorgan injury in COVID-19 patients." (PMID 34204735, 2021). "Since comorbidities are associated with chronic inflammation and are closely related to the renin–angiotensin–aldosterone system (RAAS), these individuals may already have a mild ACE1/ACE2 imbalance before viral infection, which increases their risk for developing severe cases of COVID-19." (PMID 34066804, 2021). "We also sorted the inflammatory signaling pathways in COVID-19-related ARDS, including those of IL-6/JAK/STAT, interferon, NF-κB, TLRs, Bruton’s tyrosine kinase, and renin–angiotensin system, and 49 target genes were included for further analysis." (PMID 35401158, 2021). "However, the use of this in vitro model has some limitations compared to the clinical setting and therefore without further animal experiments and/or human studies we cannot exclude that modulators of the angiotensin renin system might still affect COVID-19 patients." (PMID 34440554, 2021). "Increased levels of gonadotropin and androgen as well as dysregulated renin-angiotensin-aldosterone system (RAAS) are commonly reported in OC and severe cases of COVID-19." (PMID 33632295, 2021). "While ACE2 serves as the host entry receptor for SARS-CoV-2, alteration of the renin–angiotensin system resulting from impaired ACE2 function following coronavirus infection and how that contributes to the development of COVID-19 cannot be overemphasized." (PMID 33057007, 2020).
COVID-19 (continued). "Besides the implications of ACE2 in the pathogenesis of COVID-19, recent studies have also suggested that the disruption of the renin-angiotensin system and/or the kallikrein-kinin system could contribute to the detrimental inflammatory phenotype observed in patients with severe COVID-19." (PMID 33050019, 2020). "The binding of SARS-CoV-2 to ACE2 can disrupt the renin–angiotensin–aldosterone system (RAAS), leading to an imbalance that may contribute to hyponatremia in COVID-19 patients." (PMID 41440513, 2025). "In animal models, vitamin D has been proven to suppress renin and, consequently, angiotensin II expression, which is considered to take part in the onset of ARDS, myocarditis, and other major complications observed in COVID-19 patients." (PMID 39861359, 2025). "Many studies have analyzed the thrombogenic mechanisms in COVID-19, including endothelium inflammation, cytokine storm, disseminated intravascular coagulation (DIC), macrophage activation syndrome (MAS) and overactivation of the renin-angiotensin system (RAS)." (PMID 39861359, 2025). "The main findings of this study emphasize the necessity of early assessment and monitoring of cardiac injury and coagulation markers in COVID-19 patients, the role of ACE2 in viral invasion, and the potential benefits of renin–angiotensin–aldosterone system inhibitors." (PMID 40587711, 2025). "Interestingly, in another study renin inhibitors had the same effect as ACE inhibitors (ACEIs) and angiotensin II type 1 receptor blockers (ARBs) in the treatment of COVID-19." (PMID 39444690, 2024). "Since the renin-angiotensin system plays an important role in the occurrence of acute respiratory distress syndrome (ARDS), which can also be seen in COVID-19 patients, it is plausible to consider the potential therapeutic use of this medication in the future for treating COVID-19 patients." (PMID 38415433, 2024). "Such a relation was confirmed in a larger population encompassing 82 COVID-19 patients, in which significantly higher AngII concentrations, but not renin, were observed in severe and critically ill patients compared to those suffering from a mild infection." (PMID 38543635, 2024). "COVID-19 patients who had chronic cardiovascular co-morbidities and administered statins or renin–angiotensin–aldosterone system inhibitors had significantly lower plasma concentrations of IL-6 than COVID-19 patients who did not have any co-morbidities." (PMID 39518552, 2024). "The predicted network showed F2, ACE, REN, and SERPIND1 as some of the interacting partners with LPARs and serving as a crucial connecting node between the receptor and the studied diseases (AD, DM, and COVID-19)." (PMID 38383841, 2024). "This is because SARS-CoV-2 infection causes angiotensin-converting enzyme (ACE) and its homolog angiotensin-converting enzyme 2 (ACE/ACE2) balance disruption and renin-angiotensin-aldosterone system (RAAS) activation, which ultimately leads to COVID-19 progression." (PMID 37748553, 2023). "Furthermore, it should be noted that the process of placentation depends on the renin–angiotensin system (RAS), and COVID-19 has been shown to have an impact on this crucial process." (PMID 37299555, 2023). "A recent review suggested that potential mechanisms of ANS dysfunction after COVID-19 may involve direct invasion of SARS-CoV-2 through neuronal or hematogenous routes, autoimmunity, persistent inflammation, hypoxia, and renin-angiotensin system imbalance." (PMID 37107929, 2023). "It has been hypothesized that the renin–angiotensin–aldosterone system and its core factor ACE2 which regulates electrolyte homeostasis may play a role in the acquisition of COVID-19." (PMID 36949510, 2023). "At the molecular level, the renin-angiotensin system is highly involved in the pathogenesis of this disease, and the expression of ACE2 receptors in various organs explains the diversity of prolonged symptoms of COVID-19." (PMID 36553888, 2022).
COVID-19 (continued). "The involvement of the renin-angiotensin system (RAS), an interaction with cholinergic neurotransmission via neuronal nicotinic acetylcholine receptors (nAChR) has also been proposed as a potential treatment target in COVID-19." (PMID 35054468, 2022). "We further identified plasma proteins discriminating COVID-19 and sepsis, for example LBP, lactoferrin, and lipocalin 2; and differential pathways including neutrophil degranulation, complement, AP-1/p38MAPK, TLR, renin-angiotensin, and the HSC lineage." (PMID 35216673, 2022). "Among them, renin–angiotensin system (RAS) inhibitors and statins, which have shown to improve endothelial function in other clinical settings, have been tested in large observational studies and randomized trials with contrasting results in COVID-19." (PMID 35268542, 2022). "Of course, our study does not exclude multiple drug therapies for COVID-19 patients, but due to the wide spectrum of drug therapies, we investigated drugs that are somehow related to the renin-angiotensin system." (PMID 36199292, 2022). "The underlying pathogenesis of COVID-19–related hyperglycemia can be described by the damage to pancreatic β-cells and decreased insulin sensitivity and altered insulin secretion due to the activation of the renin-angiotensin system (RAS) and the host’s inflammatory response to COVID-19." (PMID 35336774, 2022). "Nevertheless, the prevalence of the use of drugs acting on the renin-angiotensin system, such as antihypertensive drugs, was not higher in COVID-19 patients than in non-COVID-19 patients after adjustments for age and sex." (PMID 33903671, 2021). "The renin-angiotensin-aldosterone system (RAAS), one of the major blood pressure regulatory pathways, could be involved in the pathogenesis of COVID-19, since SARS-CoV-2 uses angiotensin-converting enzyme-2 (ACE2) as the binding receptor to enter the cell." (PMID 34489863, 2021). "Higher plasma Ang II level was reported in COVID-19 patients with severe symptoms compared to mild cases, whereas other investigators detected no alterations in the serum levels of renin–angiotensin–aldosterone system peptides in COVID-19 cases." (PMID 34384355, 2021). "The main connection between renin–angiotensin system (RAS) and COVID-19 is ACE2." (PMID 34674775, 2021). "In view of the central role of ACE-2 receptor in cellular viral entry of SARS-CoV-2, in combination with the importance of the renin-angiotensin-aldosterone-system (RAAS) in maintaining endothelial homeostasis, a putative effect of inhibition of ACE and AT2 on COVID-19 severity has been proposed." (PMID 34054876, 2021). "Moreover, most of the patients with pre-existing heart disorders use renin–angiotensin–aldosterone system (RAAS) blockers, which are suggested to increase the COVID-19 severity and MR80,81." (PMID 33542313, 2021). "Although traditionally a rare condition, PRES is likely to be more common among patients with COVID-19 pathobiology there is Renin downregulation of ACE2 receptors, involvement of Renin-Angiotensin-Aldosterone system, endotheliitis, cytokine storm, and hyper-immune response." (PMID 33584499, 2021). "By regulating the activity of the renin–angiotensin system and the expression of the angiotensin-2 converting enzyme (ACE2), which decreased pulmonary permeability in an ARDS experimental model, vitamin D may counteract the harmful effects of COVID-19." (PMID 36769240, 2023). "Adding the IFN response, Renin-Angiotensin mechanism, and NLRP3 pathways from the C19DMap to an existing macrophage polarisation model helped elucidate the innate immune response that macrophages trigger upon acute COVID-19, in addition to highlighting their contribution to the disease’s pathology." (PMID 38414974, 2023).